OCLN (occludin)
Diseases named in the same sentence as OCLN in open-access papers (continued):
Sharing a sentence is not in itself a finding about the gene and the disease.
ulcerative colitis (36 papers, 2012 to 2026). An inflammatory bowel disease involving the mucosal surface of the large intestine and rectum. "Clinical studies have demonstrated the association of increased OCLN gene expression with inflammatory bowel disease, such as ulcerative colitis." (PMID 40292217, 2025). "Modified Gegen Qinlian decoction has been shown to improve symptoms and pathological damage in ulcerative colitis model mice by up-regulating occludin and ZO-1 expression." (PMID 41049135, 2025). "In this research, we assessed the utility of occludin, claudin-2, and zonulin measurements in evaluating the disease activity among patients with ulcerative colitis and Crohn’s disease." (PMID 39407507, 2024). "Low expression of zonula occludens-1 (ZO-1), E-cadherin, and occludin (OCLN) was found in the mucosa of ulcerative colitis patients together with activation of caspase-3 and GSDME." (PMID 39513865, 2024). "Consistent with our findings, it has been shown that Astragalus polysaccharide (AP) and Matrine ameliorate histopathological changes in rats with ulcerative colitis, with increased expression of ZO-1, occludin, and TFF3 in lung and colon tissues." (PMID 39588099, 2024). "An investigation of the distribution of TJ proteins in the colon tissue of DSS-induced ulcerative colitis mice was carried out using IHC of ZO-1 and occludin." (PMID 37375714, 2023). "The expression of occludin has shown variability in intestinal biopsies of patients with Crohn’s disease (CD) and ulcerative colitis (UC), suggesting inconsistent patterns in occludin expression within these studies." (PMID 37745643, 2023). "Occludin is a crucial tight junction protein in the pathogenesis of ulcerative colitis, which plays an important role in maintaining the integrity of intestinal mucosal barrier." (PMID 29234405, 2017). "Reduced expression of intestinal occludin protein and mRNA was observed in patients with ulcerative colitis and CD, suggesting the possible involvement of occludin in the pathogenesis of IBD." (PMID 27118991, 2016). "Occludin is down-regulated in patients with Crohn’s Disease and ulcerative colitis, two common types of inflammatory bowel disease in humans, suggesting the important role of occludin in intestinal health." (PMID 26664943, 2015). "IFN-γ, a pro-inflammatory cytokine, reduces TER in part through reduction of occludin levels and is thought to be involved in the pathology of celiac sprue enteropathy and inflammatory bowel disease (ulcerative colitis and Crohn’s disease)." (PMID 22553939, 2012). "Phocaeicola faecalis FXJYN30E22 showed beneficial effects in the treatment of ulcerative colitis, such as anti‐inflammatory effects, with the increase in the concentration of junctional proteins such as ZO‐1, claudin‐1, and occludin, and SCFA such as acetate and butyrate." (PMID 41312788, 2026). "Similarly, in patients with ulcerative colitis, expressions of Occludin, Claudin-1, and -4 are found to be reduced." (PMID 41031160, 2025). "Consequently, this reduces the expression of tight junction (TJ) proteins, including ZO-1 and occludin, thereby maintaining the integrity of the intestinal barrier and decreasing the occurrence of ulcerative colitis." (PMID 39940867, 2025). "Moreover, occludin protein expression was downregulated in the colorectal tissues of patients with ulcerative colitis (UC) and Crohn's disease, as was claudin-1 protein expression in the colon of patients with UC." (PMID 38368407, 2024). "Increasing evidences demonstrated that intestinal mucosal barrier dysfunction was critical in Ulcerative Colitis development and tight junction proteins (ZO-1 and Occludin), the key components of intestinal barrier, played important roles in the maintenance of intestinal permeability and integrity." (PMID 37533828, 2023). "Moreover, it has been observed that claudin-1/4 and occludin are downregulated in the intestinal epithelia of patients with ulcerative colitis." (PMID 36212959, 2022).
ulcerative colitis (continued). "Tight junction proteins (ZO-1, occludin, etc.)may be indicators used to evaluate the degree of intestinal inflammation and predicting mucosal healing in patients with ulcerative colitis." (PMID 35630568, 2022). "Likewise, it is reported that patients with active Crohn's disease or ulcerative colitis and impaired intestinal permeability have decreased expression of occludin as well as claudin 4, 5, 7, and 8, whereas claudin 2 is strongly upregulated." (PMID 32793187, 2020). "Moreover, the ability of LDP to upregulate tight junction proteins, including ZO-1 and Occludin, suggests a potential mechanism by which it could exert its therapeutic effects in ulcerative colitis." (PMID 40717964, 2025). "Occludin protein plays an indispensable role in the formation of intestinal mucosal barrier and the expression of occludin is significantly reduced in some intestinal diseases such as Crohn’s disease and ulcerative colitis, suggesting that occludin could protect the intestinal barrier." (PMID 34564656, 2021). "It demonstrated that POG effectively alleviated the decrease of Occludin, Claudin-3, and ZO-1 protein levels in the DSS-induced mice ulcerative colitis model." (PMID 35662727, 2022). "Disruption of tight junctions is an important basis for the pathogenesis of ulcerative colitis, and dysfunction of the MSP/RON pathway leads to disruption of the intestinal mucosal barrier, so occludin, a major protein in tight junctions, was examined." (PMID 29234405, 2017). "These cytokines reduce TER in part through reduction of occludin levels and increase passage of high molecular weight molecules eg the endotoxin LPS which may be involved in pathology of celiac sprue enteropathy and inflammatory bowel disease (ulcerative colitis and Crohn’s disease)." (PMID 22553939, 2012). "Research has repeatedly shown that the intestinal epithelial barrier is compromised in ulcerative colitis (UC) when ZO-1, Claudin-1, and Occludin, essential TJ proteins, are not expressed normally." (PMID 38201190, 2024). "Consequently, we examined the distribution of occludin and ZO-1 in the colon tissues of mice with DSS-induced ulcerative colitis using IHC, and observed a significant protein decrease in the N.C. group, which was prevented by FTB." (PMID 37375714, 2023). "In a study of ulcerative colitis (UC) in a rat model, EPA and DHA were found to attenuate the disruption of TJ structure by elevating expression and preventing redistribution of tight junction proteins such as occludin and ZO-1." (PMID 24066055, 2013). "The expression levels of Occludin and ZO-1 protein in colon tissue of DSS group mice were significantly decreased, indicating that the tight junction of intestinal mucosal barrier was destroyed after the establishment of ulcerative colitis model, which was consistent with previous research results." (PMID 39296302, 2024). "As expected, the VK2 administration substantially alleviated the ulcerative colitis, and it was mainly by decreasing the DAI index, increasing the expression of anti-inflammatory factor IL-10, muc2, and tight junction proteins (ZO-1, occludin), and by improving the intestinal tissue architecture." (PMID 36769323, 2023).
Obesity (34 papers, 2013 to 2025). Accumulation of substantial excess body fat. "Obesity is closely linked to inflammation, as fat accumulation and localized inflammation reduce the expression of tight junction proteins (e.g., claudin-1, occludin, and ZO-1), thereby increasing intestinal permeability and triggering inflammation." (PMID 40535017, 2025). "In contrast, we here report a dramatic loss of Occludin in the distal ileum occuring upon HFD feeding independently of obesity and inflammation." (PMID 23977107, 2013). "Specifically, it downregulates pro-inflammatory cytokines (e.g., TNF-α, IL-1β, and IL-6) while upregulating anti-inflammatory IL-10 and tight junction proteins (e.g., ZO-1 and OCLN), thereby reducing systemic inflammation and metabolic endotoxemia associated with obesity." (PMID 41365537, 2025). "Research findings in mice indicate that HFD intake reduces the expression of epithelial TJ proteins such as claudins, occludin, and ZO-1, contributing to intestinal hyperpermeability, which is linked to conditions such as diabetes, obesity, and inflammatory bowel disease (IBD)." (PMID 39728485, 2024). "In the animal model of high-fat diet and obesity, Lachnospiraceae, mainly Blautia, was significantly decreased, which increased intestinal permeability by reducing the expression of genes encoding tight junction proteins ZO-1 and Occludin." (PMID 36235611, 2022). "We determined whether underlying obesity caused an alteration of tight junction proteins in the distant ileum by Claudin-2 and Occludin immunofluorescence analysis." (PMID 32927823, 2020). "Furthermore, the dissociation of these HFD-associated effects from obesity was supported by the finding that SWR/J mice exhibited reduced ileal Occludin protein levels upon HFD in the same experimental setting, despite their resistance toward HFD-induced obesity." (PMID 23977107, 2013). "Elevated expression of genes CLDN1, OCLN, and ZO1 encoding tight junction proteins to enhance intestinal permeability in obesity." (PMID 40129979, 2025). "Previous studies have shown that Akk-EVs increase the protein expression of occludin, improve intestinal barrier integrity, alleviate obesity, and inhibit liver inflammation." (PMID 40877018, 2025). "Elevated LPS levels in individuals with obesity and T2D contribute to metabolic endotoxemia, which, in turn, downregulates intestinal tight junction proteins such as occludin and zonula occludens-1, further compromising the epithelial barrier." (PMID 41228453, 2025). "CPA4-1 and fenofibrate were tested to ameliorate changes in retinal capillaries and retinal occludin expression in db/db mice, a mouse model of obesity-induced type 2 diabetes." (PMID 32708791, 2020). "In our study, CB 0313.1 significantly restored obesity-induced down-regulation of claudin-1 and occludin at both transcriptional and protein levels." (PMID 27123997, 2016). "SNP also alleviated HFD induced obesity and gut dysfunction in mice, as indicated by the decreasing of intestinal permeability, the increasing expression of ZO-1 and occludin, the decreasing levels of pro-inflammatory cytokine IL-6, and the repairing of gut microbiota dysbiosis." (PMID 34600475, 2021). "In fact, IFN-γ decreases the expression of occludin and zonula-1 (ZO-1) in the intestinal epithelium, promoting the breakdown of the intestinal barrier, and the translocation of pathogenic bacteria and their products to the blood and VAT, favoring obesity and insulin resistance." (PMID 32774333, 2020). "The effect on occludin could be of importance for the action of the Lingon2 diet, as barrier integrity and gut leakage seem to be linked to the negative metabolic effects of HF feeding and obesity-associated low-grade inflammation." (PMID 27125264, 2016). "The mRNA level of intestinal TJ proteins, such as ZO1 and occludin, could be directly decreased by saturated fat in HFD, thereby increasing intestinal permeability in mice with HFD-induced obesity." (PMID 37371485, 2023).
Obesity (continued). "Furthermore, in mice with HFD-induced obesity, deoxycholic acid (DCA), as the primary component of BA, was found to decrease occludin expression and switch the protective claudin protein into the leaky claudin protein in the intestine, claudin-3, and claudin-2." (PMID 37371485, 2023).
inflammatory bowel disease (32 papers, 2012 to 2026). A spectrum of small and large bowel inflammatory diseases of unknown etiology. "Butyric acid, for example, has been shown to reduce diarrhea caused by intestinal barrier dysfunction, such as inflammatory bowel disease, as well as to increase the levels of occludin and cingulin proteins in HeLa cells." (PMID 37762181, 2023). "Disruptions in occludin expression or function are implicated in various diseases, including inflammatory bowel diseases where the intestinal barrier is compromised." (PMID 37834178, 2023). "Pathologic states such as inflammatory bowel disease are associated with a leaky gut epithelial barrier, disruption of TJs, and dysregulation of occludin." (PMID 34696320, 2021). "Claudin-1, ZO-1 and Occludin are typical structural proteins of epithelial tight junction, the higher expression of these proteins indicates there was decreasing risk of inflammatory bowel diseases." (PMID 27304828, 2016). "Literature research shows that reduction of tight proteins such as claudins (Cldn), Zona occludin-1 (ZO1), and occludin (Ocln) can cause inflammatory bowel disease (IBD)." (PMID 31443182, 2019). "In intestinal epithelial cells, AHR activation improves intestinal barrier function by maintaining tight junction proteins (ZO-1, Occludin, and Claudin-1) and alleviates inflammation by inhibiting NF-κB, thereby improving inflammatory bowel disease." (PMID 41513604, 2026). "The current results were in line with a study on inflammatory bowel disease in humans with the downregulation of Occludin." (PMID 36386709, 2022). "Dysfunction of the intestinal barrier in patients with inflammatory bowel disease (IBD) is associated with disturbance in the expression or distribution of several TJ proteins, including occludin and claudins." (PMID 34483933, 2021). "It is possible that comorbid conditions other than HIV, such as gastrointestinal (GI) malignancies or inflammatory bowel disease, contributed to abnormal gut barrier and hence elevated occludin levels in our study participants." (PMID 34696320, 2021). "A downregulation of OCLN expression has been observed in different intestinal models, in which the permeability was strongly altered [i.e., inflammatory bowel disease (IBD), ulcerative colitis], and was downregulated." (PMID 32373631, 2020). "Both internalization of occludin and IL-13 induced claudin-2 upregulation have also been reported in human and experimental inflammatory bowel disease models." (PMID 27467505, 2016). "Previous studies have shown intestinal tissue expression and distribution of occludin to be markedly decreased in patients with intestinal permeability disorders, including inflammatory bowel disease and irritable bowel syndrome." (PMID 25775153, 2015). "The increase in the abundance of norank_f__Erysipelotrichaceae has a causal relationship with a lower risk of inflammatory bowel disease, and it is negatively correlated with inflammatory factors such as TNF-α, while positively correlated with occludin and ZO-1." (PMID 40809052, 2025). "Inflammatory bowel disease (IBD) is strongly related to gut barrier functionality, and β-carotene reduces systemic markers of inflammation and increases occludin expression in the colon." (PMID 40646961, 2025). "Ruminiclostridium 5 and Lachnospiraceae NK4A136 are related to inflammatory bowel disease, and Lachnospiraceae NK4A136 may also affect the expression of ZO-1 and occludin protein, thereby affecting the intestinal barrier." (PMID 36506546, 2022). "In particular, TNF-α plays a critical role in inflammatory bowel disease, where it can synergize with IFN-γ to regulate multiple tight-junction (TJ) proteins, including myosin light chain kinase, occludin, and ZO-1, as well as claudin-1 and claudin-2 (106, –, 109), which are also regulated by IL-17." (PMID 32958528, 2020).
Hyperglycemia (23 papers, 2008 to 2025). An increased concentration of glucose in the blood. "We demonstrated that hyperglycemia significantly repressed occludin expression, which is associated with dysfunctional translocation of occludin and ZO-1 in db/db mice with early-stage of DN, prior to mesangial expansion." (PMID 24244596, 2013). "Additionally, we observed interactions involving KRT19, SNAI1, and OCLN that suggest a potential association of hyperglycemia with fibrosis-related pathways in TM." (PMID 39764143, 2024). "We think it is likely that this oxidative stress of the intestine disrupts the occludin-ZO-1 complex-associated intestinal barrier and thus increases systemic influx of LPS, leading to chronic inflammation-associated IR, a typical feature of T2D, and subsequent hyperglycemia and related indexes." (PMID 35987753, 2022). "Hyperglycemia impairs the expression of Occludin (a tight junction protein) in the retinal vasculature during the onset of diabetic retinopathy." (PMID 40002391, 2025). "Ins2Akita retinas show alterations in tight junction proteins, including downregulation of ZO-1 and occludin expression, as well as altered distribution of occludin in retinal blood vessels starting after 2 months of hyperglycemia." (PMID 36869375, 2023). "Based on these observations, we concluded that Azilsartan protected against hyperglycemia-induced hyperpermeability of BBB via the KLF2/occludin axis." (PMID 34266350, 2021). "In summary, our data show that Azilsartan prevents hyperglycemia-induced hyperpermeability of the BBB by activating the KLF2/occludin signaling pathway." (PMID 34266350, 2021). "Our data showed that the levels of occludin and claudin-5 obviously decreased 1d after injury, and hyperglycemia significantly aggravated these reductions, along with those of p120 and β-catenin, both in vivo and in vitro." (PMID 28794417, 2017). "The changes in abundance shown in this study highlight potential roles for claudin‐1 and occludin in the action of metformin to prevent the P. aeruginosa‐induced increase in glucose permeability and hyperglycaemia‐induced growth." (PMID 26837005, 2016). "For example, hyperglycemia impairs the expression or function of ZO-1/occludin, and this leads to diabetic retinopathy." (PMID 24244596, 2013). "Simvastatin prevented high glucose or hyperglycemia-induced dysregulation of occludin and ZO-1 by inhibition of RhoA/ROCK1 signaling in cultured GEnCs and in db/db mice with early-stage DN." (PMID 24244596, 2013). "In contrast, we found that endothelial occludin expression is down-regulated in response to hyperglycemia." (PMID 24244596, 2013). "Similarly, in human intestinal organoids, HA35 counteracts hyperglycemia-induced barrier disruption by preserving zonula occludens-1 (ZO-1) and occludin localization through the HA receptor, layilin." (PMID 41305610, 2025). "Compared with the control group, the ZO-1 and occludin protein expression levels were significantly decreased in the hyperglycemia group, and were significantly increased in the TET2 shRNA transfection group, as compared with the control shRNA transfection group." (PMID 37430272, 2023). "Moreover, hyperglycaemia down‐regulated ZO‐1 and Occludin in RPE cells." (PMID 31094072, 2019). "Our study highlights the potential of metformin to reduce hyperglycaemia‐induced P. aeruginosa growth through airway epithelial tight junction modulation, and that claudin‐1 and occludin could be important targets to regulate glucose permeability across airway epithelia and supress bacterial growth." (PMID 26837005, 2016). "We also investigated the effects of hyperglycemia on gene expression of tight junction proteins ZO-1 (TJP1), Claudin 1 (CLDN1), and Occludin (OCLN)." (PMID 38110453, 2023). "We evaluated the potential effect of transient hyperglycemia on the expression of tight junction proteins ZO1, CLDN1, and OCLN." (PMID 35220596, 2022).